CTLA4 (cytotoxic T-lymphocyte associated protein 4)
Diseases named in the same sentence as CTLA4 in open-access papers (continued):
Sharing a sentence is not in itself a finding about the gene and the disease.
tumor (continued). "In recurrent BRCA-deficient OC patients, a combination of PARPi and CTLA-4 blockade (tremelimumab) led to decreased tumor size with grade 1 and 2 toxicities." (PMID 37368179, 2023). "Immune checkpoint inhibitors (ICI) revolutionized cancer therapy by augmenting anti-tumor immunity via cytotoxic T-lymphocyte-associated protein 4 (CTLA-4) and programmed death-1/programmed death-ligand 1 (PD-1/PD-L1)." (PMID 38203586, 2023). "While anti-CTLA4 monotherapy can induce some degree of antitumor activity, the presence of Tregs, low mutation burden, and high expression of PD-L1 in the tumor microenvironment can limit its effectiveness." (PMID 37376141, 2023). "Cytotoxic T-lymphocyte-associated protein-4 (CTLA-4) is an immune checkpoint receptor that downregulates anti-tumour immune responses, with evidence of involvement in HNC." (PMID 36980582, 2023). "It was generally believed that anti-CTLA-4 antibodies caused tumor rejection by promoting the priming of naïve T cells through blocking the inhibitory B7-CTLA-4 signaling in peripheral lymphoid organs." (PMID 37251931, 2023). "Monoclonal antibodies targeting cytotoxic T lymphocyte-associated antigen 4 (CTLA4) and the programmed death-1 (PD-1) receptor and its ligand programmed death-ligand 1 (PD-L1) have been approved as the standard of care in different tumor sites." (PMID 38021572, 2023). "The discovery of programmed cell death 1 (PD-1), programmed cell death 1 ligand 1 (PD-L1) and cytotoxic T lymphocyte-associated protein-4 (CTLA-4) has promoted the development of tumor immunotherapy." (PMID 37261523, 2023). "A combined gene signature comprising the three CD8+ T cell clusters expanded in the tumor of mice treated with radiation and CTLA4 inhibition is associated with survival in patients." (PMID 37620372, 2023). "These biological characteristics of tumor cells are related to the host immune system, such as PD-L1 and programmed cell death protein 1 (PD-1), in proportion to the upregulation of cytotoxic T-lymphocyte-associated protein 4 (CTLA-4)." (PMID 37631987, 2023). "Regarding tumour immunotherapy, we are especially focused on two inhibitory checkpoints: cytotoxic T-lymphocyte-associated protein 4 (CTLA-4) and programmed death protein 1 (PD-1)." (PMID 38136332, 2023). "Recent data demonstrate that Fc γR-mediated antibody-dependent cellular cytotoxicity (ADCC) is a critical, and perhaps dominant, mechanism underlying anti-CTLA-4 activity in the tumor microenvironment." (PMID 37753969, 2023). "Suppressive immune checkpoints such as programmed death-1 (PD-1) and cytotoxic T-lymphocyte associated antigen-4 (CTLA-4) can be exploited either directly or indirectly by tumour cells to avoid elimination by the anti-tumour immune response." (PMID 36980582, 2023). "Assessing germline variants in GBM patients’ blood by sequencing and determining the transcript levels of Fc-γRIII in the tumor will be immediate steps necessary to investigate the relevance of Fc-γR polymorphisms with anti–CTLA-4 therapies in GBM." (PMID 36647828, 2023). "CAF subsets with distinct extracellular matrix (ECM) programs are associated with T cell exclusion from the tumor and correlate with PD-1+ and CTLA4+ CD4+ T cell content in tumor lesions." (PMID 37086273, 2023). "Metastatic involvement of tumor draining lymph nodes has been associated with immune suppressive features including hampered DC activation, increased Treg CTLA-4 expression, and elevated PD-1 expression." (PMID 37568665, 2023). "Some cell adhesion molecules also mediate tumor immune evasion, such as cytolytic T lymphocyte-associated protein-4 (CTLA-4) and programmed cell death protein-1 (PD-1)/programmed cell death-ligand 1 (PD-L1), which are also called immune checkpoint." (PMID 36895477, 2023).
tumor (continued). "It has been recorded that a lack of efficacy of the anti-PD-1 and a modest clinical benefit of the anti-PD-L1 plus the anti-CTLA-4, reserved only to patients with a tumor mutational burden (TMB) more than 28 mut/Mb on circulating tumor DNA." (PMID 37658314, 2023). "Intrinsic CTLA-4 expression has also been linked to BC cell proliferation, differentiation, survival, and the stem-cell-like phenotype in different neoplasms." (PMID 36901916, 2023). "The analysis was specifically focused on regulatory T cells (Tregs) and their expression of immune checkpoint cytotoxic T-lymphocyte associated protein 4 (CTLA-4) as key contributors to tumour immune evasion, which undermines antitumour immune responses." (PMID 36319895, 2023). "Anti-programmed cell death protein 1/programmed cell death ligand 1 (anti-PD-1/PD-L1) and anti-cytotoxic T-lymphocyte-associated protein 4 (anti-CTLA-4) are the most commonly used tumor immunotherapy approaches." (PMID 37916161, 2023). "As is well known, tumor immune escape is linked to crucial immunological checkpoint proteins, including CTLA-4 and PDCD-1." (PMID 36899339, 2023). "Immune checkpoint inhibitors (ICIs) such as anti-programmed cell death 1 receptor (anti-PD1) and anti-cytotoxic T-lymphocyte-associated protein 4 (anti-CTLA4) fail to elicit effective anti-tumour responses in the vast majority of CRC patients." (PMID 37563222, 2023). "For example, the blockade of CD73, a checkpoint associated with adenosine metabolism that suppresses anti-tumor immune responses, can enhance the therapeutic efficacy of anti-CTLA-4 and anti-PD-1." (PMID 37106400, 2023). "PD-1 is a member of CTLA-4 (cytotoxic T lymphocyte-associated protein 4) family, primarily expressed by cytotoxic T cells (Tc), which predominate anti-tumour responses." (PMID 37397243, 2023). "These unsatisfactory outcomes are linked to immunosuppressive tumor microenvironments, such as checkpoint receptor signaling (PD-1/PD-L1, CTLA-4), and immune suppressive cells, such as Tregs and MDSCs." (PMID 36596856, 2023). "RP2 expresses an anti-CTLA-4-like antibody as a means to optimize immune priming at the tumor site while reducing the risk of immune-related adverse events associated with systemic anti-CTLA-4 therapy." (PMID 37841530, 2023). "Molecular biomarkers such as TMB (tumor mutation burden), CTLA-4 (cytotoxic T lymphocyte-associated antigen-4), PD-1/PDL1 (Programmed cell death 1 ligand 1) have been gradually incorporated into clinical guidelines." (PMID 37752452, 2023). "This suggests that a methyltransferase inhibitor/anti-PD-1+anti-CTLA-4 (cytotoxic T-lymphocyte-associated antigen 4) intervention can be used to inhibit tumor growth." (PMID 36226062, 2022). "Hypoxia also increases the expression of T cell immunoglobulin domain and mucin domain-3 (TIM-3) and CTLA4 on Tregs and tumor-associated macrophages (TAMs), leading to immunosuppression." (PMID 36559202, 2022). "Despite the precise mechanisms and pathways being yet to be fully elucidated, tumour cells are able to express CTLA-4 to cause the transduction of an apoptotic signal to T cells." (PMID 35626149, 2022). "This limits their anti-tumor activity and induces the expression of immune regulatory molecules cytotoxic T-lymphocyte associated protein 4 (CTLA-4) and programmed cell death 1 (PD-1)." (PMID 35327609, 2022). "Apart from this, there are other classification tools to stratify patients, such as molecular subtypes, PD-1, PD-L1, CTLA-4, and tumor mutation burden (TMB)." (PMID 35833141, 2022). "Currently, approved checkpoint inhibitors target mainly the programmed cell death protein 1 (PD-1) axis or cytotoxic T-lymphocyte-associated protein 4 (CTLA-4) to reinvigorate anti-tumour immunity." (PMID 36266575, 2022).
tumor (continued). "Analysis of tumor-infiltrating lymphocytes (TILs) implicated that anti-CTLA4 predominantly mediated a decrease in the Treg compartment, whereas anti-PD-L1 promoted a strong increase in CD8+ TILs." (PMID 36497086, 2022). "ICIs block the interaction between cytotoxic T lymphocyte-associated antigen-4 (CTLA-4), programmed cell death protein 1 (PD-1), and their cognate ligands and thus generate immune responses to tumor cells." (PMID 36032051, 2022). "Subsequently, we identified a hub gene, TBC1D10C, that correlated with OS and the PFI and had a high positive association with tumor-infiltrating immune cells and three common immune checkpoints (PD-1, CTLA-4, and TIGIT)." (PMID 35425695, 2022). "A high CTLA-4+ cell density was linked to low pT category (p < 0.0001), absent lymph node metastases (p = 0.0354), and PD-L1 expression in tumor cells or inflammatory cells (p < 0.0001 each)." (PMID 35091676, 2022). "Given the suboptimal anti-tumor activity of single agent ICPIs in EP-NECs, approaches with dual ICPIs that target programmed cell death 1 (PD-1) and cytotoxic T-lymphocyte-associated protein 4 (CTLA-4) have been evaluated." (PMID 35681675, 2022). "In HPV-negative metastases, the amount of PD-L1+ tumor cells was favorably associated with prognosis, while patients with a higher density of CTLA-4+ cells in the stroma had a shorter DFS." (PMID 36123711, 2022). "Combined immune checkpoint blocking (CICB) therapy targeting CTLA-4 and PD-1 is associated with high clinical benefits across tumor types, but unfortunately, the incidence of irAEs is also higher with the widespread use of CICB." (PMID 36189293, 2022). "Nowadays, tumor immune checkpoint inhibitors (ICIs), including programmed death receptor 1 (PD-1), PD-ligand 1 (PD-L1), and cytotoxic T-lymphocyte-associated protein 4 (CTLA-4), have revolutionized NSCLC treatment." (PMID 35359393, 2022). "Programmed cell death protein 1 (PD-1), programmed cell death one ligand 1 (PD-L1) and cytotoxic T-lymphocyte-associated protein 4 (CTLA-4) are essential immune checkpoints for tumor immune escape." (PMID 35309118, 2022). "A common feature associated with anti-CTLA-4–mediated tumor rejection is an increase in the ratio of T effector to T regulatory cells within the tumor." (PMID 35053602, 2022). "Regarding immune checkpoints associated with tumor cell immune evasion, such as CTLA-4, PD-1, PD-L1, TIGIT, these inhibitory receptors/ligands suppress antitumor immune responses by altering their expression levels." (PMID 36276981, 2022). "Although tumor loss of IFN-γ signaling has been defined as a major mechanism of resistance to anti-CTLA-4 9 and anti-PD-110–14, little effort has been devoted to overcome this ICB resistance." (PMID 36008408, 2022). "They showed that expression of CTLA-4 in lymphocytes improves prognosis while expression of this protein in tumor cells is associated with poor prognosis." (PMID 35054356, 2022). "Cytotoxic T lymphocyte-associated protein 4(CTLA-4) surface trafficking has recently gained a great attention in the field of tumor immunotherapy, and the precise regulatory mechanisms and vital regulatory sites of CTLA-4 are still emerging." (PMID 36528587, 2022). "It is known that CTLA-4 is mainly expressed on Tregs cells, this is consistent with the higher abundance of Tregs in the tumor microenvironment of high-risk ccRCC." (PMID 35155251, 2022). "ICIs target programmed cell death-1 (PD-1) and cytotoxic T lymphocyte-associated antigen 4 (CTLA-4) on T cells or their ligands, such as programmed cell death 1 ligand-1 (PD-L1) on tumor cells to enhance antitumor T cell activity." (PMID 36428666, 2022). "ICIs targeting PD-1/PD-L1 and CTLA-4 have caused a revolution in cancer care by reversing the immunosuppressive tumor microenvironment." (PMID 36613817, 2022). "Hypoxia is associated with tumor resistance to T cell infiltration even in the context of CTLA-4 and PD-1 blockade." (PMID 36233088, 2022).
tumor (continued). "The expression of immune checkpoints, including PD-1, PD-L1, and CTLA-4, has been associated with tumor aggressiveness and poor prognosis." (PMID 35932027, 2022). "Compared to patients with an HRR wild type (HRRwt), those with HRR mutations (HRRmut) in anti-CTLA-4-treated patients of the Samstein2018 cohort had higher tumor mutation burden (TMB; P = 0.0041) and longer median overall survival (mOS; P = 0.0094)." (PMID 35990677, 2022). "TME composition at relapse significantly associated with an increase of CTLA4 gene counts normalized to tumor-infiltrating CD3 gene counts but not of FoxP3 gene." (PMID 36038629, 2022). "Here remains the pathophysiological mechanism of the use of immune checkpoint inhibitors (ICIs), which bind to CTLA-4 and PD-1 to activate immune cells from a quiescent state to cause a reaction against tumor cells." (PMID 35775000, 2022). "While combinational P407 hydrogel-based ICG-PDT and CTLA-4 blockade therapy significantly reduced tumor growth when undergo multiple times irradiation, displayed the highest tumor elimination proportions associated with strong anti-tumor immune responses." (PMID 35974207, 2022). "CTLA-4 resides on tumor cells at various densities and triggers apoptosis associated with the sequential activation of caspase-8 and caspase-3." (PMID 35281086, 2022). "Previous studies showed that PDCD1 (PD1), CD274 (PDL1), and CTLA-4 were closely associated with immune escape in the tumor microenvironment." (PMID 35273591, 2022). "The binding of T cell immune checkpoint proteins programmed death 1 (PD-1) and cytotoxic T-lymphocyte-associated protein 4 (CTLA-4) to their ligands allows immune evasion by tumours." (PMID 35228677, 2022). "Interferons’ counterregulatory effects can also increase the production of immunological checkpoint molecules by tumor cells, such as galectin 9 and cytotoxic T lymphocyte-associated antigen 4 (CTLA-4), as well as programmed cell death 1 ligand 1 (PD-L1)." (PMID 36498574, 2022). "Immune checkpoint molecules, such as cytotoxic T lymphocyte associated antigen-4 (CTLA-4) and programmed cell death-1 (PD-1) on the T cell surface, play a critical role in tumor immune escape." (PMID 35565217, 2022). "Immune checkpoint blockade (ICB) strategies targeting immunosuppressive proteins including cytotoxic T-lymphocyte-associated antigen 4 (CTLA-4) have been shown to achieve marked clinical efficacy in a range of tumor types." (PMID 35568916, 2022). "Accordingly, inhibition of tumor glycolysis ameliorates the ability of CTLA-4 blockade to induce loss of Treg stability associated with the development of anti-tumor immunity." (PMID 35874810, 2022). "ICI therapy represented by PD-1 and CTLA-4 inhibitors has undoubtedly caused a breakthrough in anti-tumour therapy." (PMID 35571047, 2022). "Immune checkpoint molecules, including cytotoxic T-lymphocyte-associated protein 4 (CTLA4), programmed cell death protein-1 (PD-1) and programmed cell death ligand-1 (PD-L1), are responsible for tumour escape from the immune response." (PMID 36685833, 2022). "Immune checkpoint blockade (ICB) generates anti-tumor response through the inhibition of cytotoxic T-lymphocyte-associated protein 4 (CTLA-4), programmed cell death protein 1 (PD-1), and/or programmed cell death protein 1 ligand (PD-L1)." (PMID 35740660, 2022). "We therefore tracked changes in circulating effector and memory T-cell subsets and accompanying phenotypic changes associated with anti-PD1 or anti-CTLA4 mediated tumor control." (PMID 36230753, 2022). "Interaction of CD86 with CTLA-4 inactivates T lymphocytes, causing the escape of tumor cells from the immune system." (PMID 35311155, 2022). "Recent advances in ICB therapy, including those targeting programmed cell death protein 1 (PD-1)/PD-ligand 1 (PD-L1) and/or cytotoxic T-lymphocyte-associated protein 4 (CTLA-4), have allowed strong enhancement of anti-tumor immune responses." (PMID 35991576, 2022).
tumor (continued). "Apart from this, there are other molecular classification tools to stratify patients, such as CTLA‐4, PD‐1, and tumour mutation burden (TMB)." (PMID 36083778, 2022). "In particular, genetic mutations, inflammatory cytokines, PD-L1 and CTLA-4 levels, and tumor-infiltrating lymphocytes (TIL) should be assessed, as their expression has been related to a favorable response to treatment." (PMID 35330068, 2022). "SQLE was significantly associated with tumor immune cell infiltration, immune checkpoints (including PD-1 and CTLA-4), and biomarkers of the TME." (PMID 35720314, 2022). "Studies have shown that patients with a higher TIDE score suggest T cell dysfunction in the tumor microenvironment, which is associated not only with poor immune checkpoint blockade treatment but also with poor survival under anti-PD-1 and anti-CTLA4 therapy." (PMID 35368661, 2022). "For example, fragile bacteriocin is a key factor in targeting the anti-tumour effect of antibodies against cytotoxic T lymphocyte-associated protein 4 (CTLA-4)." (PMID 35782150, 2022). "Programmed cell death protein-1 (PD-1) and cytotoxic T-lymphocyte–associated protein 4 (CTLA-4) are two important immune checkpoints that can impede anti-tumor response when combined with their receptors." (PMID 35800432, 2022). "In the myeloid compartment, we observed that anti-CTLA-4 treatment caused a shift of F4/80+ macrophages to F4/80- Ly6C+ monocytes in both tumor types." (PMID 35523809, 2022). "In patients with cancer, tumors often control immune checkpoints (such as CTLA-4 or PD-1/PD-L1) to cause T cell dysfunction or inhibition which blocks the host anti-tumor immune response to protect tumor tissue." (PMID 35309935, 2022). "Low CRG_scores were characterized by high tumor mutation burden and immune activation, good survival probability, and more immunoreactivity to CTLA4, while high CRG_scores were characterized by the activation of stromal pathways and immunosuppression." (PMID 35979353, 2022). "Tumor immunophenotyping 1 week after treatment indicated loss of Foxp3+ regulatory T (Treg) cells in response to CTLA4 across genotypes." (PMID 36344707, 2022). "Increased levels of CTLA-4 have also been reported in canine melanocytic tumors and associated with an immune-suppressed tumor microenvironment leading to immune escape and worsened prognosis." (PMID 36686160, 2022). "Recent studies have shown that loss of ARID1A expression sensitises tumours to CTLA4 and PD-1 immune checkpoint inhibition." (PMID 35393414, 2022). "ICIs are monoclonal antibodies targeting the programmed cell death protein 1 (PD1), the programmed death ligand 1 (PDL1), and/or the cytotoxic T lymphocyte-associated protein 4 (CTLA-4), enhancing the immune system response against tumor cells." (PMID 36077631, 2022). "These agents can block the cytotoxic T-lymphocyte–associated antigen 4 (CTLA-4)/B7 or the programmed death 1 (PD-1)/programmed cell death-ligand 1 (PD-L1), leading to T-cell mediated tumor cell destruction." (PMID 36430703, 2022). "Immune checkpoint inhibitors (ICI) including programmed death-1 (PD-1) inhibitors, programmed death ligand-1 (PD-L1) inhibitors, and cytotoxic T-lymphocyte associated protein 4 (CTLA-4) inhibitors promote immune-mediated targeted killing of tumour cells." (PMID 36547123, 2022). "The presence of immunosuppressive molecules- such as CTLA-4 and PD-L1 is another important cause of tumor immunosuppression." (PMID 35401561, 2022). "Among ICIs, the representative (PDCD1,PD-1) inhibitor, its (CD274,PD-L1) inhibitor, and cytotoxic T-lymphocyte associated protein 4 (CTLA4) restore the ability of immune cells to fight tumors by counteracting the inhibition of the immune system by tumor cells." (PMID 35600371, 2022). "In mouse models, the anti-tumor efficacy of CTLA-4 antibodies has been linked to their ability to deplete CTLA-4+ Treg cells." (PMID 35379805, 2022).